HOTAIR (HOX transcript antisense RNA)
Diseases named in the same sentence as HOTAIR in open-access papers (continued):
Sharing a sentence is not in itself a finding about the gene and the disease.
cancer (continued). "Furthermore, lncRNAs are important factors in the control of gene expression in cancer, and lncRNAs such as HOTAIR have been shown to play an important role in the development and progression of tumors." (PMID 25089627, 2014). "Transcriptional up-regulation of the human HOTAIR gene in cancer involves epigenetic mechanisms." (PMID 25491133, 2014). "In conclusion, our study found that HOTAIR might be a novel predictive factor for assessing poor prognosis in different types of cancer both in Asian and western countries." (PMID 25157956, 2014). "Combining these HRs suggests that HOTAIR expression might be an independent prognostic factor for cancer patients (pooled HR 2.26, 95%CI: 1.62–3.15), but a significant heterogeneity was detected among studies (χ2 = 27.25, df = 11, p = 0.004, I2 = 59.6%)." (PMID 25157956, 2014). "Several studies have shown a relationship between high HOTAIR expression and the poorer prognosis of diverse cancers 14–22, but there are few studies that reveal the importance of Hox-related genes and/or HOTAIR in SCLC because of the scarcity of fresh tissue samples." (PMID 24591352, 2014). "HOTAIR shows great prognostic and therapeutic promise for various kinds of cancer." (PMID 25334066, 2014). "Therefore, we conducted a systematic review and quantitative meta-analysis to clarify the prognostic value of HOTAIR expression in human cancers." (PMID 25157956, 2014). "It is necessary therefore to clarify the relationship between HOTAIR and cancer." (PMID 25303230, 2014). "Increasing evidence suggests that HOTAIR regulates key pathways in cancer invasion and metastasis." (PMID 23936419, 2013). "Conversely, knockdown of HOTAIR or PRC2 component expression can inhibit cancer invasiveness." (PMID 24103700, 2013). "Regulation of the expression of HOTAIR in cancer remains unclear and is investigated in the current study." (PMID 23668363, 2013). "The role of HOTAIR in promoting oncogenesis has also been reported in other cancers." (PMID 24013378, 2013). "Since HOTAIR plays an important role in the epigenetic regulation of its target genes, it is not surprising that its deregulation has been observed in different types of cancers." (PMID 24013378, 2013). "In 26 pairs of cancer and matching non-cancer tissues from patients with NSCLC, the RNA levels of HOTAIR in cancer tissues exhibited a 4.8-fold increase over that in the corresponding non-cancer tissues (P = 0.002 as determined using paired two tail student T test)." (PMID 23668363, 2013). "HOTAIR was shown to play a role in cancer metastasis and may be an indicator of poor prognosis in patients with primary breast cancer." (PMID 23455466, 2013). "HOTAIR as an epigenetic regulator in gene expression is deregulated in different cancers." (PMID 23443164, 2013). "Therefore, our present findings are consistent with previous studies indicating that the expression of HOTAIR is involved in the enhanced aggressiveness of various types of carcinoma cells." (PMID 24130837, 2013). "In addition to creating and maintaining spatiotemporally patterned HoxD expression in multiple tissues during embryogenesis, HOTAIR is also involved in aberrant gene expression in cancers." (PMID 21496275, 2011). "However, the mechanisms by which HOTAIR influences gene regulation in cancer are poorly understood." (PMID 42239237, 2026). "Notably, LncRNAs such as HOTAIR have shown promise in influencing cancer progression and may serve as valuable tools for therapeutic intervention." (PMID 41459628, 2026). "Notably, lncRNAs like PCA3, HOTAIR, and CTBP1-AS are linked to AR pathway stimulation, with HOTAIR promoting cancer growth by directly interacting with AR, inhibiting its ubiquitination and degradation, and enhancing AR target gene expression independently of androgens." (PMID 40290121, 2025). "This suggests that HOTAIR may be an oncogene in different types of cancer." (PMID 40642606, 2025).
cancer (continued). "Thus, HOTAIR may affect the immunity of different cancers and do so through potential distinct mechanisms." (PMID 38696320, 2024). "Interestingly, the pan-cancer analysis also revealed a markedly poor survival in tumors with high HOTAIR expression, which indicated that HOTAIR might participate in tumorigenesis." (PMID 38696320, 2024). "Furthermore, some reports have indicated that HOTAIR SNP rs920778 exhibits variable results in the same population but in distinct cancer types such as gastric and breast, which suggests that there are variations in the polymorphism throughout different malignancies." (PMID 38587571, 2024). "In addition, HOTAIR acts as a ceRNA that sponges microRNAs and reverses the repression of their targets, resulting in a complex cross-talk between overexpressed HOTAIR and various microRNAs that affect cancer cell proliferation, migration, and invasion." (PMID 38339237, 2024). "Thus, our study aims to investigate the association of HOTAIR rs920778, MIR155HG rs1893650, TERC rs10936599, miR-155 rs767649, miR-196a2 rs11614913 and miR-146a rs2910164 genetic variations with the cancer risk, progression, and progression-free survival of PTC patients." (PMID 38339237, 2024). "Also, treatment of cancer (MDA‐MB‐231) cells derived from TNBC with phenolic compound such as Delphinidin‐3‐glucoside could halt HOTAIR expression both in vivo and in vitro." (PMID 37795578, 2023). "Despite a large body of evidence highlighting the aberrant HOTAIR expression in the progression of different cancers (e.g. breast, colorectal, nasopharyngeal, liver, gallbladder, gastrointestinal and pancreatic cancers), the mechanisms controlling its transcription are still only partially unveiled." (PMID 37308974, 2023). "In addition, HOTAIR has been demonstrated to influence the EMT process in a range of cancers." (PMID 36120580, 2022). "In addition, by stimulating hexokinase-2 (HK2) expression, HOTAIR may be engaged in the processes of cancer cell energy metabolism, including glucose uptake, lactate production, and ATP production." (PMID 35565245, 2022). "Hence, variations in isoform composition likely results in cell type specific structures and interactomes, which could account for the divergent roles of HOTAIR in primary cells and cancer cell lines." (PMID 36115964, 2022). "This evidence suggests that m6A may play a role in cancers where HOTAIR is overexpressed." (PMID 36441764, 2022). "Therefore, screening a larger library of natural and synthetic compounds to identify compounds that target the interaction between HOTAIR and PRC2 complexes could be an alternative strategy for targeting HOTAIR/ EZH2-dependent cancers." (PMID 36100611, 2022). "Furthermore, the expression level of HOTAIR could be suppressed by inhibitors to limit the metastatic potential of cancer, which also indicated that HOTAIR has therapeutic value as an efficient drug target." (PMID 33621953, 2021). "The most well-known lncRNA is HOTAIR, a oncogene in human cancer, its 5ʹ domain could bind polycomb repressive complex 2, while its 3ʹ domain bound the LSD1/CoREST/REST complex, thereby controlling target gene expression via specifying the pattern of histone modifications." (PMID 34699314, 2021). "Thus, HOTAIR knockdown exhibits great therapeutic potential in various cancers, indicating that targeting lncRNA HOTAIR may serve as a promising strategy for cancer therapy." (PMID 34367966, 2021). "In addition, it was reported that the expression of HOTAIR in cancer cells can be enhanced by OPN." (PMID 33670447, 2021). "In addition, miR-214-3p expression was significantly increased when HPV16 E7 expression was knocked down, but once HPV16 E7 gene was up-regulated expression again in cancer cells, HOTAIR expression went up also and the expression trend of miR-214-3p was obviously reversed." (PMID 34320988, 2021). "Likewise, HOTAIR silencing leads to reduced cell migration abilities of cancer cells." (PMID 32466537, 2020).
cancer (continued). "HOTAIR is one of the most well-studied oncogenic lncRNAs, whose overexpression has been correlated with poor prognosis and overall patients’ survival in various cancer types, including liver, colon, hepatocellular, lung, gastric, pancreatic, breast, and esophageal squamous cell carcinomas." (PMID 32932969, 2020). "Similarly to MALAT1, HOTAIR also functions as a sponge miRNA to regulate gene expression in cancer." (PMID 32283739, 2020). "Furthermore, histone methylation is known to be affected by inhibitors of DNA methylation, such as 5-Aza-2′-deoxycytidine which is used as an anti-cancer drug, and it would be interesting to investigate the effects of applying such compounds on HOTAIR signalling in OA." (PMID 32650720, 2020). "Moreover, HOTAIR is often overexpressed and may serve as a promising biomarker of distant metastasis in various cancer types." (PMID 32928281, 2020). "Thus, HOTAIR can be considered a potential therapeutic target for the reversal of resistance to conventional chemotherapeutics in patients with different types of cancer." (PMID 31174564, 2019). "Taken together, these findings provide persuasive evidence that HOTAIR-mediated modulation of cancer epigenome could be remodeled by a small compound to reverse tumor growth and metastasis affording new insights for the development of novel therapeutic approaches in clinical epigenetics." (PMID 31367244, 2019). "Therefore, HOTAIR may play opposite roles in regulating cancer behaviors in different pathological processes." (PMID 31113870, 2019). "Therefore, based on our findings, HOTAIR could serve as a potential biomarker for the prediction of cancer patient survival in many different types of human cancers." (PMID 31195674, 2019). "However, the interaction between PACER and HOTAIR characterized in the present study may guide the studies on the function of HOTAIR in other diseases, such as cancer." (PMID 31113870, 2019). "Therefore, HOTAIR is deemed to be a potential biomarker for cancers." (PMID 30459803, 2018). "Therefore, the knockout of the HOTAIR gene or decreasing the protein level of HOTAIR could provide a hopeful target for cancer therapy." (PMID 29299179, 2017). "Furthermore, silibinin may exert its anti-cancer effects by suppressing oncogenic lncRNAs such as HOTAIR and ZFAS1." (PMID 29190895, 2017). "HOTAIR inhibition may be a potential option for cancer prevention and CSC targeted therapies." (PMID 29299179, 2017). "Thus, HOTAIR is a key LncRNA in genesis and development of cancer." (PMID 27965458, 2017). "In addition, HOTAIR was also shown to be involved in the progression of multiple types of cancers, indicating that HOTAIR might serve as a useful biomarker for tumorigenesis and progression." (PMID 28938673, 2017). "Indeed, HOTAIR was identified as a prognostic marker of metastasis in diverse human cancers." (PMID 27095571, 2016). "In addition, HOTAIR preferentially occupies a GA-rich DNA motif to nucleate broad domains of polycomb occupancy and altered histone H3 lysine 27 methylation, gene expression, and increased cancer invasiveness." (PMID 27167190, 2016). "Conversely, downregulation of HOTAIR may decrease the metastasis and invasion of cancer cells." (PMID 27897239, 2016). "Furthermore, HOTAIR is involved in the resistance of cancer cells to cisplatin." (PMID 25859406, 2015). "However, HOTAIR has been suggested as a biomarker for most cancer types." (PMID 25859406, 2015). "Furthermore, we investigated the roles of HOTAIR in E2-induced cancer cell migration." (PMID 25928008, 2015). "Thus, conducting a meta-analysis of HOTAIR expression in all cancer types may help in the identification of the cancers that have the highest probability of HOTAIR overexpression." (PMID 25859406, 2015). "Hence, HOTAIR expression level can be used as a potential prognostic factor for various cancers." (PMID 25859406, 2015). "Furthermore, HOTAIR has been reported to regulate cancer cell cycle progression." (PMID 25428914, 2015).
cancer (continued). "However, although HOTAIR has been shown to play a vital role in cancer, the factors that contribute to its upregulation and the interaction between HOTAIR and miRNAs are largely unknown." (PMID 24953832, 2014). "Moreover, HOTAIR is involved in the aberrant regulation of gene expression in cancer." (PMID 21496275, 2011). "Numerous lncRNAs, including HOTAIR, MALAT1, and PVT1, are crucial in a wide range of cancers and have significant clinical relevance." (PMID 40723840, 2025). "Researchers are developing inhibitors or agonists targeting specific lncRNAs (e.g., HOTAIR, MALAT1) and circRNAs (e.g., circRNA CDR1as) to restore or suppress their functions, inhibiting cancer cell proliferation and metastasis." (PMID 40621472, 2025). "Our work advances the field by: Establishing HOTAIR as a novel pro-inflammatory driver in ALI, expanding its known roles beyond cancer and chronic diseases." (PMID 41567340, 2025). "PTX‐resistant cancer cells were divided into PTX + EVs‐si‐NC, PTX + EVs‐si‐HOTAIR + oe‐NC, and PTX + EVs‐si‐HOTAIR + oe‐CDH2." (PMID 40235720, 2025). "Specifically, we analyze the functions of lncRNAs, including HOTAIR and MALAT1, in key processes such as apoptosis, DNA damage response and repair, cancer stem cell regulation, and drug metabolism." (PMID 41276852, 2025). "HOTAIR and ANRIL are prominent lncRNAs that substantially influence drug resistance, metastasis, and cancer." (PMID 41013839, 2025). "HOTAIR interacts with EZH2 and is upregulated in a variety of cancers (breast, lung, colon and gastric)." (PMID 40868070, 2025). "Instead, lncRNA MAFG-AS1 and HOTAIR enhance COX2 expression by acting as ceRNAs that sponge miR-101 and miRNA-143-3p, respectively, both of which target COX2 3′UTR and prevent cancer progression." (PMID 40429961, 2025). "Other lncRNAs, including HOTAIR, ZEB2-AS1, and UCA1, have been shown to regulate apoptosis and growth in various cancer types by sponging specific miRNAs that target HMGB1 expression." (PMID 40429961, 2025). "HOTAIR (HOX Transcript Antisense RNA) is a lncRNA located within the HOXC gene cluster and is widely acknowledged for its oncogenic functions in various cancers." (PMID 40723840, 2025). "Investigations concerning UCA1 and HOTAIR, analogous to those on MALAT1, have primarily concentrated on the downregulation of these lncRNAs and the subsequent diminution in cancer progression." (PMID 40699668, 2025). "TCGA analysis also yielded similar results, showing elevated expression of HOTAIR and EZH2 in advanced EC (Stage III&IV) compared to early-stage cancer (Stage I&II), with a positive correlation between HOTAIR and EZH2 expression (r = 0.18, P = 0.019)." (PMID 41353219, 2025). "HOTAIR, for instance, has been extensively studied for its ability to promote EMT by silencing genes that inhibit metastasis, enabling cancer cells to detach and spread to other parts of the body." (PMID 40231344, 2025). "HOTAIR silencing in MDA-MB-231 and Hs-578t cancer cell lines inhibits 3D channel-like network formation and cell migration." (PMID 40277941, 2025). "On the other hand, HOTAIR and UCA1 play significant roles in cancer development and progression, primarily through epigenetic mechanisms like miRNA sponging or by recruiting specific chromatin remodelers." (PMID 38279264, 2024). "As outlined in the manuscript, several lncRNAs, such as HOTAIR, MEG3, and MALAT1, have shown strong correlations with cancer progression, metastasis, and resistance to therapies." (PMID 39512820, 2024). "Many cellular processes in cancer stem cells (CSCs) that are known to initiate tumor formation can be regulated by lncRNAs such as MALAT1, ROR, HOTAIR, H19, UCA1 and ARSR." (PMID 39199690, 2024). "Therapeutically, ASOs and siRNA targeting oncogenes like HER2, KRAS, and VEGF, as well as lncRNAs such as HOTAIR and MALAT1, and circRNAs like circPVT1 and circ_0000523, can inhibit cancer-promoting pathways and reduce tumor growth and metastasis." (PMID 39857631, 2024).
cancer (continued). "Furthermore, a study published in 2016 highlighted that the T allele of HOTAIR rs920778 was significantly associated with an increased risk of developing cancer in Asians but not in a Turkish population, emphasizing the importance of ethnicity in this type of studies." (PMID 38275875, 2024). "The HOX transcription antisense intergenic RNA (HOTAIR), has been described as a positive promoter of the PI3K/AKT and Wnt/β-catenin signaling pathways in several types of cancer, even in the presence of drugs and specific inhibitors for these pathways." (PMID 39273054, 2024). "Key lncRNAs such as HOTAIR, NEAT1, and MALAT1 have now been discovered to drive the progression of many cancers." (PMID 37267628, 2023). "In cervical cancer, HOTAIR promotes EMT, migration and resistance to chemotherapeutics by sponging miR-29b, thus counteracting the inhibitory role of this miRNA on cancer progression." (PMID 37308974, 2023). "It has been found that HOTAIR upregulation promotes hexokinase 2 (HK2) expression, a protein that plays a pivotal role in energetic cancer metabolism." (PMID 37189687, 2023). "Mechanistically, HOTAIR has been shown to promote metastasis by regulating EMT and enhancing cancer cell invasion and migration." (PMID 36997931, 2023). "Thus, HOTAIR may promote cancer cell energy metabolism by upregulating HK2 expression." (PMID 37189687, 2023). "The lncRNA ANRIL is involved in cancers, diabetes, and cardiovascular disease, lncRNA H19 in atherosclerosis, coronary artery diseases, regulation in blood pressure, and cancer, lnc-NR2F in developmental disorders, and HOTAIR in cancers." (PMID 35378133, 2022). "The correlation of HOTAIR with cancer malignancy and poor prognosis is related to CRC and several cancers like pancreatic cancer, epithelial ovarian cancer, mammary cancer, and hepatocellular carcinoma." (PMID 36699052, 2022). "LncRNAs, such as HOTAIR, H19, LncTCF7, LUCAT1, MALAT1, LINC00511, and FMR1-AS1, have been described as key regulators of stemness in cancer, allowing cancer cells to acquire this phenotype." (PMID 35954194, 2022). "One of the best studied lncRNAs with this function is HOTAIR (HOX transcript antisense RNA), which mediates the silencing of tumor suppressor genes such as P21 in cancer." (PMID 35954194, 2022). "For example, high expression of HOTAIR, MALAT1, and CCAT2 is related to poor prognosis in various cancer types." (PMID 35892331, 2022). "In conclusion, we verified the differential expression of HOTAIR and CCL22 in cancer tissues and adjacent normal tissues in NSCLC patients, and there was a strong negative correlation between HOTAIR and CCL22 mRNA expression." (PMID 35176085, 2022). "Here, we investigated the contribution of HOTAIR in cisplatin-induced cancer cachexia and dissected the potential signaling cascade involving the epidermal growth factor receptor (EGFR), ProT, NF-κB, and HOTAIR." (PMID 36471329, 2022). "Recent studies show that various lncRNAs, such as HOTAIR, MALAT1, NRAL and TUG1, play a pivotal role in the regulation of cancer cells’ oxidative stress, highlighting a possible crossroad between lncRNAs and ROS." (PMID 36077530, 2022). "Some of the lncRNA with good potential in cancer diagnosis or prognosis include PCA3, MALAT1, HOTAIR, H19, and CCAT1." (PMID 35892331, 2022). "MALAT1, HOTAIR, H19, HOTTIP, ANRIL, and NEAT1 are among the most famous lncRNAs which have been mostly studied in many types of cancer exhibiting dysregulation in cancer cells, tissues and body fluids of affected patients." (PMID 35281110, 2022). "Surprisingly, at a subset of genes, the A783U mutant induces opposite gene expression changes to WT HOTAIR, reducing molecular and cellular cancer phenotypes in TNBC cells, indicating that the mutant HOTAIR can function as an antimorph." (PMID 36441764, 2022).